CLDN10 (claudin 10)
Diseases named in the same sentence as CLDN10 in open-access papers (continued):
Sharing a sentence is not in itself a finding about the gene and the disease.
gastric cancer (continued). "Moreover, we analyzed and compared the immune infiltration levels among gastric cancer patients with the presence of different SCNA status for CLDN10." (PMID 34721537, 2021). "And CLDN10 may serve as a potential prognostic biomarker and correlate to immune infiltration levels in gastric cancer." (PMID 34721537, 2021). "The effect of CLDN10 expression in gastric cancer, however, has yet to be elucidated." (PMID 34721537, 2021). "However, to date, the clinical significance of CLDN10 expression in gastric cancer has remained unclear." (PMID 34721537, 2021). "In exhausted T cells, these gene markers (PD1, CTLA4, LAG3, TIM3 and GZMB) were consistently significantly correlated with the expression of CLDN10, which further suggested that the expression level of CLDN10 in gastric cancer is related to immune infiltration." (PMID 34721537, 2021). "Correlations of CLDN10 expression and clinicopathological significance in gastric cancer." (PMID 34721537, 2021). "Furthermore, the immunohistochemical pictures provided by the HPA database indicated that CLDN10 was localized in the cytoplasm and membrane, and his protein expression level in gastric cancer was also lower than that in normal tissues." (PMID 34721537, 2021). "With regard to lymph node metastasis, we found that the expression of CLDN10 was statistically correlated with OS and PFS in all stage except stage N2, suggesting that the abnormal expression of CLDN10 may be related to lymph node metastasis of gastric cancer." (PMID 34721537, 2021). "Thus, the objective of this study was to examine the expression of claudin-10,-14, -17 and E-cadherin in gastric carcinoma and adjacent tissue which have been less well studied." (PMID 24325792, 2013). "For example, claudin-1 is associated with colon cancer prognosis, claudin-18 is related to gastric cancer (GC) prognosis, and claudin-10 is relevant to hepatocellular carcinoma prognosis." (PMID 38511141, 2024). "In addition, we analyzed and verified the expression level of CLDN10 in gastric cancer samples and cell lines, and the results were consistent with the online database, further confirming the down-regulation role of CLDN10 in gastric cancer." (PMID 34721537, 2021). "Moreover, data from Oncomine and UALCAN confirmed that CLDN10 was down-expressed in gastric cancer." (PMID 34721537, 2021). "Lastly, we detected the mRNA expression level of 10 paired GC tissues and adjacent normal tissues and GC cell lines by Real-Time PCR to verify the down-regulation of CLDN10 in gastric cancer." (PMID 34721537, 2021). "The expression of CLDN10 was statistically correlated with OS and PFS in stage M0 gastric cancer, while only OS in stage M1." (PMID 34721537, 2021). "The correlations between CLDN10 expression and immune cell infiltration and somatic copy number alternations (SCNA) in gastric cancer were explored by TIMER2.0 and GEPIA2.0." (PMID 34721537, 2021). "Our results showed that CLDN10 expression significantly correlated to the expression of B cells (CD19, CD79A) and Tfh cells (BCL6, IL21) markers, which indicated a potential mechanism for CLDN10 to regulate B cell function in gastric cancer." (PMID 34721537, 2021). "In this study, expression of claudin-10, 14, 17 and was studied in 50 cases of gastric carcinoma and adjacent non-neoplastic tissues adjacent to the gastric carcinoma tissues." (PMID 24325792, 2013). "In addition, CLDN10 expression was associated with OS and PFS in HER2-negative gastric cancer patients (OS p = 2.1e-07; PFS p = 0.00033), but not with HER2-positive patients." (PMID 34721537, 2021).
clear cell renal cell carcinoma (5 papers, 2021 to 2024). "Our previous study has proved that down-regulation of CLDN10 (Claudin-10) in ccRCC (clear cell renal cell carcinoma) was closely related to tumor metastasis and predicted an unfavorable prognosis by analyzing TCGA-KIRC data." (PMID 35414767, 2022).
ichthyosis (5 papers, 2019 to 2025). Disorders of cornification that are characterized by visible scaling and/or hyperkeratosis of most or all of the skin. "Hadj-Rabia described mild forms of ichthyosis with a thickened stratum corneum, palmar hyperlinearity and plantar keratoderma in two unrelated families with different CLDN10 variants." (PMID 31671507, 2019). "It is well documented that biallelic mutations in Claudin-10 cause HELIX, an acronym for the manifestations of Hypohidrosis, Electrolyte imbalance, lacrimal gland dysfunction, ichthyosis, and Xerostomia." (PMID 40242686, 2025). "At present it remains unsolved whether dermatological manifestations such as ichthyosis and dry skin are a mere consequence of sweat gland dysfunction or may also be augmented by defective claudin-10 proteins in the epidermis." (PMID 31671507, 2019).
lung carcinoma (5 papers, 2007 to 2021). "In contrast, low expression of CLDN10 indicated a poor prognosis in lung cancer patients." (PMID 34631779, 2021). "c-fos is considered a recognized oncogene, CLDN10 may control the invasion and metastasis of lung cancer cells by inhibiting the c-fos pathway." (PMID 34631779, 2021). "Expression of CLDN10 may be regulated by the c-fos pathway, which is related with lung cancer progression." (PMID 23591077, 2013).
breast carcinoma (4 papers, 2010 to 2026). "Members of the claudin family of tight junction proteins are epigenetically silenced in human breast cancer; expression of claudin 10 was decreased by -81.2 fold in SRC1-/- mammary tumors." (PMID 21080969, 2010). "Knockdown of CLDN10 in brain endothelial cells significantly reduces transendothelial resistance and increases barrier permeability, facilitating both drug delivery and the transendothelial invasion of breast cancer cells." (PMID 41399659, 2026). "Importantly, breast cancer cells with low CLDN10 expression showed enhanced ability to cross the brain endothelial barrier, suggesting that CLDN10 downregulation may promote brain metastasis." (PMID 41399659, 2026).
lung adenocarcinoma (4 papers, 2013 to 2025). A carcinoma that arises from the lung and is characterized by the presence of malignant glandular epithelial cells. "Among seven genes that displayed different expression patterns, claudin-10, a component of tight junction strands, was chosen for functional analysis because it has been reported to be associated with lung adenocarcinoma." (PMID 29145406, 2017). "A microarray analysis of the B-1 lymphocytes revealed that IL-10 deficiency is associated with down-regulation of the genes that code for claudin-10, a protein that is involved in cell-to-cell contact and that has been linked to lung adenocarcinoma." (PMID 29145406, 2017). "Immunohistochemical staining for these genes in samples from 81 cases of lung adenocarcinoma demonstrated the expressions of CLDN1 and CLDN10 were correlated with overall survival of patients with lung adenocarcinoma." (PMID 23591077, 2013). "Overexpression of CLDN1 and CLDN10 indicates a favorable prognosis for overall survival in some patients with lung adenocarcinoma." (PMID 23591077, 2013). "Our study suggested that the expression of claudin 1(p = 0.105) and claudin 10(p = 0.027) may fuction as cancer cell invasion and metastatic suppressor in lung adenocarcinoma through c-fos signal pathway." (PMID 23591077, 2013). "Four genes (MMP-2, c-fos, claudin 1 (CLDN1) and claudin 10(CLDN10)) were correlated with the results of microarray and real time RT-PCR analyses for the gene-expression data in samples from 41 patients with lung adenocarcinoma." (PMID 23591077, 2013).
thyroid cancer (4 papers, 2013 to 2025). "A higher expression of TMPRSS6 or CLDN10 individually could be detected in other tumors (B respectively), while a higher combined expression was observed in ovarian serous cystadenocarcinoma (OV), thyroid carcinoma (THCA), and uterine corpus endometrial carcinoma (UCEC) apart from LUAD." (PMID 35178045, 2021). "However, CLDN10 expression was higher in cholangiocarcinoma (CHOL), adenocarcinoma (LUAD), lung squamous cell carcinoma (LUSC) and thyroid carcinoma (THCA) than in the adjacent normal tissues." (PMID 34721537, 2021).
xerostomia (4 papers, 2022 to 2025). Dryness of the mouth resulting from reduced salivary secretion. "Taken together, our data show that enamel formation is not significantly impaired by CLDN10 deficiency, rather designating xerostomia as the main culprit of the enamel wear found in HELIX patients." (PMID 35902997, 2022).
nephrocalcinosis (3 papers, 2024 to 2025). Nephrocalcinosis is a disorder that occurs when too much calcium is deposited in the kidneys. "Conversely, thick ascending limb–specific KO of claudin-10 reduces fractional excretion of calcium, presumably by increasing thick limb reabsorption of calcium, and leads to outer medullary nephrocalcinosis despite hypocalciuria." (PMID 41066193, 2025). "The injury caused by nephrocalcinosis cannot explain the complex phenotype of Trpv5 Atp6v1b1 dKOs, especially since other mouse models with nephrocalcinosis (Cldn2 KO and Cldn10 ksp cKO) do not develop this severe pathology." (PMID 38339056, 2024).
osteosarcoma (3 papers, 2020 to 2022). A usually aggressive malignant bone-forming mesenchymal neoplasm, predominantly affecting adolescents and young adults. "CLDN10 is highly expressed in osteosarcoma cells compared with fetal osteoblast cells, and CLDN10 overexpression in osteosarcoma cells enhances the JAK1/STAT1 signaling pathway to significantly promote proliferation and motility." (PMID 36620607, 2022). "For instance, overexpression of CLDN10 in osteosarcoma may be related to its metastatic phenotype." (PMID 32045884, 2020).
head and neck cancer (2 papers, 2021). A primary or metastatic malignant neoplasm affecting the head and neck. "The role of SLURP1 and CLDN10 in head and neck cancer has not been described." (PMID 34631779, 2021).
Hypomagnesemia (2 papers, 2019 to 2024). An abnormally decreased magnesium concentration in the blood. "Another finding that should be commented upon, pertaining to the CLDN16 gene interaction network, is the identification of the CLDN10 gene as recently it was reported that deletion of the latter rescues CLDN16-deficient mice from hypomagnesemia and hypercalciuria." (PMID 31357502, 2019).
idiopathic pulmonary fibrosis (2 papers, 2019). Idiopathic pulmonary fibrosis (IPF) is a nonneoplastic pulmonary disease that is characterized by the formation of scar tissue within the lungs in the absence of any known cause. "CLDN10 is believed to have a role in idiopathic pulmonary fibrosis (IPF) progression." (PMID 30940135, 2019).
infertile (2 papers, 2012 to 2022). "There is an intriguing possibility that the altered localization and increased expression of claudin-10, especially in ovarian endometriosis, might contribute to infertility via disturbed ion homeostasis." (PMID 36428908, 2022). "Interestingly, Cldn10 mRNA expression is altered in patients with obstructive azoospermia and the localization of Cldn10 in the epididymal epithelium is modified in infertile patients with non-obstructive azoospermia." (PMID 22511979, 2012).
kidney cancer (2 papers, 2022 to 2025). Primary or metastatic malignant neoplasm involving the kidney. "In this study, we examined CLDN10 expression in a large number of clinical ccRCC and mccRCC samples, and determined that CLDN10 expression was generally lost in kidney cancer." (PMID 35414767, 2022). "However, there are few studies on the roles of CLDN10 in kidney cancer." (PMID 35414767, 2022).
lymph node metastasis (2 papers, 2020 to 2021). "Although the high expression of CLDN10 is associated with lymph node metastasis, it provided better predictions for PTC." (PMID 32045884, 2020). "Due to lack of available data, the relationship between differential expression of CLDN10 and lymph node metastasis was not explored in detail; ii." (PMID 34721537, 2021).
melanoma (2 papers, 2017 to 2026). A malignant, usually aggressive tumor composed of atypical, neoplastic melanocytes. "Thus, the identification of claudin-10 as a mediator of the pro-metastatic effect of B-1 lymphocytes on melanoma cells reveals a potential target for the development of molecular therapeutics to control the melanoma metastasis." (PMID 29145406, 2017). "Together, these data support the hypothesis that homotypic interactions mediated by claudin-10 are required to trigger the more metastatic behavior on B16F10 melanoma cells after contact with B-1 lymphocytes." (PMID 29145406, 2017). "Finally, to further confirm the role of claudin-10 in bringing out the changes that are observed in the melanoma cells after contact with B-1 lymphocytes, the claudin-10 expression was inhibited in the B16F10 cells." (PMID 29145406, 2017). "Thus, our findings suggest that the axis IL-10/claudin-10 is a promising target for the development of therapeutic agents against aggressive melanoma." (PMID 29145406, 2017). "Thus, our results demonstrate that the axis IL-10/claudin-10 is a suitable target to control the behavior of melanoma cells." (PMID 29145406, 2017). "Thus data from the present work corroborated the previous findings that established an association between the ERK signaling and the tumor aggressiveness and, supporting the notion that claudin-10 is involved in the changes in melanoma cells upon contact with B-1 lymphocytes." (PMID 29145406, 2017). "In summary, our findings demonstrate that endogenous IL-10 influences the expression of claudin-10 in B-1 lymphocytes and implicate the axis IL-10/claudin-10 to augment the aggressive behavior of the B16F10 melanoma cells upon contact with B-1 lymphocytes." (PMID 29145406, 2017). "Using this pipeline, we identified CLDN10 and GJB2 as potential tumor suppressors in melanoma." (PMID 41828699, 2026). "In addition, similar results were recorded when claudin-10 was inhibited in the B16F10 cells, validating the role of claudin-10 as a mediator to increase the metastatic potential of B16F10 melanoma after contact with B-1 lymphocytes." (PMID 29145406, 2017). "Thus, our findings demonstrate that claudin-10 is a key mediator in the interplay between B-1 lymphocytes and B16F10 melanoma cells and is involved in the enhancement of melanoma aggressiveness upon contact with the B-1 cells." (PMID 29145406, 2017). "Similarly, increase in claudin-10 expression in the B16F10 cells upon contact with B-1 lymphocytes was also inhibited, indicating that the ERK pathway is involved in the expression of claudin-10 in the melanoma cells." (PMID 29145406, 2017). "As hypothesized, in the absence of claudin-10, B-1 lymphocytes were unable to modulate the metastatic behavior of the B16F10 melanoma cells." (PMID 29145406, 2017).
prostate carcinoma (2 papers, 2012 to 2013). A carcinoma that arises from epithelial cells of the prostate gland. "In the present study, we found increased CLDN10 mRNA transcript abundance in the PP adipose tissue of prostate cancer patients using both microarray and real-time PCR analyses." (PMID 23009291, 2012).
abortion (1 paper, 2022). the ending of pregnancy by removing a fetus or embryo before it can survive outside the uterus. "We evaluated the expression of claudin-2, claudin-3, and claudin-10 in the uterine samples from IL-22−/− and WT mice after LPS-triggered abortion." (PMID 36091010, 2022).
adenomyosis (1 paper, 2022). The growth of endometrial tissue inside the muscular wall of the uterine corpus. "Recently, we suggested that the endometrial glands are the main source of adenomyotic glands because of the highly identical protein pattern in the endometrium compared to that in adenomyosis, which we similarly observed in the case of claudin-10." (PMID 36428908, 2022). "A significantly higher expression of claudin-10 was evident in the ectopic endometrium of deep-infiltrating (p < 0.01) and ovarian endometriosis (p < 0.001) and in adenomyosis in the cases with endometriosis (p ≤ 0.05)." (PMID 36428908, 2022). "The significant differences in claudin-10 localization between the three endometriotic entities and adenomyosis, in conjunction with endometriosis, suggest that most of the aberrations occur after implantation and not before." (PMID 36428908, 2022). "The high similarity between the claudin-10 patterns in the eutopic endometrial and adenomyotic glands supports our recent conclusions that the endometrium is the main source of endometriosis and adenomyosis." (PMID 36428908, 2022). "Furthermore, we also showed that the expression of claudin-10 was significantly higher in the ectopic endometrium, especially in ovarian endometriosis, as well as in adenomyosis in cases with coexisting endometriosis." (PMID 36428908, 2022). "In order to better understand the possible contribution of claudin-10 to the endometrial epithelial phenotype and its role in the pathogenesis of adenomyosis and endometriosis, we analyzed claudin-10 localization based through immunohistochemistry in this study." (PMID 36428908, 2022). "Our results convincingly demonstrate that claudin-10 is expressed in nearly all the eutopic, ectopic endometrial, and adenomyotic glands, although we noted a reduction in the eutopic endometrium in the cases with endometriosis and adenomyosis." (PMID 36428908, 2022). "In this study, we identified similar high expressions of claudin-10 in nearly all the eutopic, ectopic endometrial, and adenomyotic glands, excepting a reduction in the eutopic endometrium among the cases with endometriosis and adenomyosis." (PMID 36428908, 2022). "However, the quantification of the percentage of claudin-10 positive glands showed a significant reduction in the number in the eutopic endometrium among the cases with endometriosis in conjunction with adenomyosis." (PMID 36428908, 2022). "Additionally, claudin-10 was found in nearly all the epithelial cells and glands in the endometrium, although there was a significant reduction in the percentage of positive glands in the endometrium in the cases with endometriosis together with adenomyosis." (PMID 36428908, 2022). "Interestingly, in our study, we identified a shift in the localization of claudin-10 from the apical membrane in the eutopic endometrium to a basal/cytoplasmic localization in the ectopic endometrium but not in adenomyosis." (PMID 36428908, 2022). "Interestingly, we observed a shift in claudin-10 from a predominant apical localization in the eutopic endometrium to a more pronounced basal/cytoplasmic localization in the ectopic endometria of all three endometriotic entities but not in adenomyosis." (PMID 36428908, 2022). "However, claudin-10 localization has never been analyzed in endometriosis or adenomyosis." (PMID 36428908, 2022). "Similarly, claudin-10 was also found mainly in the apical cell poles and in nearly all the glands, as well as in nearly all the epithelial cells of the eutopic endometrium in the cases with and without endometriosis and all the cases that presented with adenomyosis." (PMID 36428908, 2022).
amelogenesis imperfecta (1 paper, 2020). Amelogenesis imperfecta (AI) represents a group of developmental conditions affecting the structure and clinical appearance of the enamel of all or nearly all the teeth in a more or less equal manner, and which may be associated with morphologic or biochemical changes elsewhere in the body. "Mutations in CLDN10, CLDN16, and CLDN19 are associated with amelogenesis imperfecta in humans and in mice, deletion of Cldn3 significantly reduces the enamel volume compared to that of wild-type mice." (PMID 33195274, 2020).
colorectal cancer (1 paper, 2010). A primary or metastatic malignant neoplasm that affects the colon or rectum. "Ten of these genes (WDR67, RFXAP, RP11-50D16.3, CAB39L, THSD1, SPRY2, TGDS, CLDN10, SLC10A2, CD33L3) have been reported changed in tumor tissues, while only 2 (RP11-50D16.3, SLC10A2) have been reported to appear changed in colorectal cancer." (PMID 20467480, 2010).